MTMR3 (myotubularin related protein 3)
Diseases named in the same sentence as MTMR3 in open-access papers (continued):
Sharing a sentence is not in itself a finding about the gene and the disease.
colon cancer (1 paper, 2014). "Furthermore, to explore the underlying signaling pathways mediated by MTMR3 in colon cancer cells, we examined 18 important and well-characterized signaling molecules using PathScan Intracellular Signaling Array kit." (PMID 25215329, 2014). "Collectively, these results strongly support that MTMR3 is essential for the growth of HCT116 colon cancer cells." (PMID 25215329, 2014). "In the present study, we aimed to investigate the role of myotubularin-related phosphatase 3 (MTMR3) in CRC cell growth via lentivirus-mediated small interfering RNA (siRNA) transduction in human colon cancer cell lines HCT116 and SW1116." (PMID 25215329, 2014). "The results revealed that knockdown of MTMR3 induced a strong proapoptotic effect in colon cancer cells." (PMID 25215329, 2014). "siRNA mediated silencing of MTMR3 has an inhibitory effect on the proliferation of colon cancer cells by inducing cell cycle arrest and apoptosis." (PMID 25215329, 2014). "In this study, we identify MTMR3 as a critical gene in the colon cancer cell survival and growth." (PMID 25215329, 2014). "Thus, we could infer that MTMR3 knockdown suppressed colon cancer cell growth through inducing cell cycle arrest and apoptosis." (PMID 25215329, 2014).
Fibroadenoma (1 paper, 2023). A benign tumor of the breast characterized by the presence of stromal and epithelial elements. "We looked into the blood expression levels of HULC and MTMR3 genes, their correlation with clinicopathological data, and their potential as non-invasive biomarkers in fibroadenoma and BC patients." (PMID 37910386, 2023). "Additionally, we looked at the serum levels of HULC and MTMR3, their connection with clinicopathological data, and their potential as non-invasive biomarkers of BC in fibroadenoma and BC patients." (PMID 37910386, 2023). "MTMR3 was a statistically significant discriminator of all four groups (except non-metastatic from metastatic): non-metastatic from fibroadenoma (cutoff > 4.18), non-metastatic from control (cutoff > 1.0), metastatic from fibroadenoma (cutoff > 1.0), and fibroadenoma from control (cutoff > 1.0)." (PMID 37910386, 2023). "Based on this, we sought to examine the relationship between the HULC rs7763881 and MTMR3 rs12537 SNPs, clinicopathological data, their correlation with the expression of HULC and MTMR3 in serum, and their association with the susceptibility to BC and fibroadenoma." (PMID 37910386, 2023).
glioblastoma (1 paper, 2022). The most malignant astrocytic tumor (WHO grade IV). "Furthermore, it was shown that FTO knockdown promotes m6A-mediated maturation of miR-10a leading to enhanced glioblastoma progression by targeting 3′-UTR of Myotubularin Related Protein 3 (MTMR3) mRNA and modulation of the Wnt/β-catenin pathway." (PMID 36012529, 2022).
metabolic myopathy (1 paper, 2020). A group of rare inherited disorders characterized by a deficiency of enzymes that are involved in metabolic pathways that affect muscles. "Interestingly, the mRNA expression level of AMPD (associated with symptoms of metabolic myopathy when it is deficient in skeletal muscle) and the MTMR3 (plays an important role in maintaining muscle function), decreased in our study, indirectly suggesting a metabolic disturbance condition in FBFGs." (PMID 32395106, 2020).
cancer (10 papers, 2012 to 2025). A tumor composed of atypical neoplastic, often pleomorphic cells that invade other tissues. "It has been shown that MTMR3 is involved in cancer cell proliferation, migration and invasion." (PMID 25415319, 2014). "Some researchers have discovered that the hot spot mutations of TERTp could trigger the aberrant expression of several cancer-related genes, such as cellular retinoic acid binding protein 2 (CRABP2), murine double minute 4 (MDM4), and myotubularin related protein 3 (MTMR3)." (PMID 39934880, 2025). "Therefore, we try to investigate the expression of MTMR3 in the cancer genome atlas (TCGA) database by UALCAN, discovering that compared to normal tissues MTMR3 was lower expressed in primary tumor tissues (p <1E-12), but the promoter methylation level was higher (p = 2.66E-02)." (PMID 34395483, 2021).
tumor (9 papers, 2014 to 2025). "The underlying mechanism might be caused by MTMR3 influencing the transition of tumor cells from G1 to S phase." (PMID 40165954, 2025). "MTMR3 belongs to the myotubularin-related protein family and is a target gene of various miRNAs that regulate tumour development." (PMID 34781885, 2021). "MTMR3 is also involved in autophagic activity, an important mechanism in the inhibition of tumor growth." (PMID 25415319, 2014). "It has been shown that MTMR3 has a role in the development of tumors, including oral and colon cancer, and that autophagy is an important intracellular mechanism that acts as a tumour inhibitor to increase cell survival by impacting tumour growth and metastasis." (PMID 37910386, 2023).
neurodevelopmental disorder (1 paper, 2020). A behavioral and cognitive disorder with onset during the developmental period that involves impaired or aberrant development of intellectual, motor, or social functions. "Two other genes (AGR3, MTMR3) have not been previously associated with ASD or neurodevelopmental disorders." (PMID 32820185, 2020).
MTMR3 also shares sentences with these, for which no sentence is quoted: inflammatory bowel disease (2 papers); lung adenocarcinoma (2); rheumatoid arthritis (2); astroblastoma (1); cardiovascular disease (1); colorectal cancer (1); dental caries (1); diabetes (1); gastrointestinal carcinomas (1); Huntington disease (1); infection (1); liver cancer (1); Myocardial fibrosis (1); Myotubular myopathy (1); periodontitis (1); psoriasis (1); pulpitis (1).